USP22 (ubiquitin specific peptidase 22)
Diseases named in the same sentence as USP22 in open-access papers (continued):
Sharing a sentence is not in itself a finding about the gene and the disease.
cancer (continued). "And RNAseq revealed that multiple genes involved in angiogenesis such as HIF1a, VEGF etc. were significantly downregulated in USP22 knockout cancer cells." (PMID 31842906, 2019). "USP22 knockdown reduces the invasiveness and metastasis of multiple cancers by downregulating pathways driven by the oncoprotein, BMI-1." (PMID 31689236, 2019). "The concomitant activation of polycomb ubiquitin ligases RNF2 and deubiquitinase USP22 is significant during cancer progression because USP22 activation allows transcriptional up-regulation of cell cycle related genes." (PMID 29934362, 2018). "USP22 is a member of the 11-gene ‘death-from-cancer’ signature that predicts cancer aggressiveness and the likelihood of treatment failure in a wide range of malignancies." (PMID 28881649, 2017). "Eleven genes were identified as death-from-cancer signatures predicting poor survival of cancer patients in multiple malignancies including USP22." (PMID 28415621, 2017). "Multiple mechanisms have been identified to explain how USP22 overexpression contributes to cancer progression, and thus, USP22 has been proposed as a novel drug target in cancer." (PMID 29210986, 2017). "Ubiquitin specific peptidase 22 (USP22), a deubiquitinating enzyme (DUB), is a member of a family of 11 gene signature-encoded proteins involved in the cancer stem cell (CSC) phenotypes of aggressive growth, metastasis and therapy resistance." (PMID 28427243, 2017). "As USP22 overexpression occurs in multiple cancer types, its possible oncogenic roles and potential as a new therapeutic target in cancer are areas of active research." (PMID 29210986, 2017). "In contrast, low-level gains and amplification of USP22 are collectively observed in only 2–20% of cases from the same cancer types." (PMID 29210986, 2017). "The high prevalence of USP22 overexpression in cancer is also challenged by the results of many additional genome-wide studies." (PMID 29210986, 2017). "In fact, in a survey of TCGA gene re-sequencing data from the 12 most deadly cancer types in North America, each cancer exhibits a greater frequency of USP22 copy number losses than gains." (PMID 29210986, 2017). "USP22, a novel deubiquitinating enzyme and a member comprising the 11 gene Polycomb/cancer stem cell signature, possesses the functions such as transcription activation, epigenetic regulation and cancer progression." (PMID 28567015, 2017). "Because USP22 was identified as a CSC marker and regulates the progression and prognosis of multiple cancers, and CSCs are responsible for cancer initiation and metastasis, we explored the effect of USP22 on GC stem-like cell (SC) formation and GC progression." (PMID 28415621, 2017). "Given that SIRT1 is a promising regulator of metabolism and autophagy, which are also significant for MDR in cancer cells, it is important to further explore the mechanism of USP22/SIRT1‐induced MDR in HCC cells." (PMID 28417539, 2017). "Clinically, USP22 has been confirmed to predict tumor recurrence, metastasis, and poor survival after cancer diagnosis in several types of cancer." (PMID 28417539, 2017). "In human CRC tissues, the genes encoding USP22 and AP4 are overexpressed in metastatic liver lesions compared with primary cancer tissues, and their overexpression is significantly associated with poor CRC patient survival." (PMID 28427243, 2017). "This initial study spurred widespread interest in the potential role and prognostic significance of USP22 overexpression in various cancer types." (PMID 29210986, 2017). "USP22 expression is correlated with cancer progression and tumor invasion, and had synergistic effects with C-myc in GC tissues." (PMID 28415621, 2017). "Hematoxylin and eosin (H&E) staining showed that the cancer cells in the control group grew well, whereas the USP22 knockdown group had large patches of necrosis in the xenografts." (PMID 28415621, 2017).
cancer (continued). "A few studies have demonstrated that USP22 overexpression promoted cancer progression and poor prognosis of glioma, pancreatic cancer, cervical cancer and lung cancer." (PMID 27030989, 2016). "Studies in human samples suggest that USP22 overexpression is involved in different pathological conditions such as cancer, neurological disorders, diabetes and male infertility." (PMID 27057639, 2016). "Several members of the DUB family are known to contribute to carcinogenesis, including USP1, USP2, USP7 and USP22, while other DUBs are down-regulated in human cancers, including USP10 and BAP1." (PMID 27030989, 2016). "In fact, USP22 knockdown in different types of cancer cells, lead to cell cycle arrest in the G0/G1 phase and decreased in-vivo tumor growth." (PMID 27057639, 2016). "In cancer cells, recruited by the Myc oncoprotein or nuclear receptors, USP22 deubiquitylates histone H2A and H2B, and is necessary to counteract heterochromatin silencing and thereby transactivate specific target genes." (PMID 27145278, 2016). "Several other studies have confirmed overexpression of USP22 at the protein level in different types of cancer as well as its correlation to poor patient survival." (PMID 27057639, 2016). "It is likely that USP22 overexpression in cancer is a downstream effect of the activation of pro-survival pathways." (PMID 27057639, 2016). "USP22 is part of the 11-gene Polycomb/cancer stem cell signature, which uniformly exhibits a marked propensity toward metastatic dissemination and a therapy resistance phenotype." (PMID 25909224, 2015). "Here, we demonstrate that crosstalk between the two putative cancer stem cell genes, USP22 and CCNB1, has an important role in colorectal tumorigenesis." (PMID 27030811, 2015). "Within the hSAGA complex, USP22 removes ubiquitin from histone H2B, thus regulating the transcription of downstream genes that are related to epigenetic alteration and cancer progression." (PMID 25909224, 2015). "As a consequence, gain of USP22 functions promotes cell cycle progression and inhibits cell apoptosis, leading to cancer cell hyper-proliferation and tumorigenesis." (PMID 27030811, 2015). "Elevated USP22 expression can predict shorter interval of tumor recurrence, distant metastasis, therapeutic failure and poor prognosis in patients with many cancer types." (PMID 25909224, 2015). "Similar to the findings of previous studies, USP22 was found to be expressed at higher levels in poorly differentiated cancer cell lines and cancer tissues and to correlate closely with HCC differentiation." (PMID 25909224, 2015). "To further support our observation that USP22 promotes cell cycle progression and probe further into its potential role in cancer development, we first examined its function in cell proliferation." (PMID 27030811, 2015). "This novel finding suggests that USP22 promotes cell proliferation via the c-Myc/cyclin D2 pathway, leading to cancer development." (PMID 24466336, 2014). "USP22 was initially identified in 2005 as a key component of the “death-from-cancer” signature, an 11-gene signature predicting for recurrence, metastasis and therapy resistance in multiple cancers." (PMID 25547493, 2014). "An increasing body of literature shows that USP22 expression is elevated in cancers and is prognostic for disease progression and treatment outcome." (PMID 25547493, 2014). "Cancer cells with reduced USP22 expression exhibited reduced proliferation and colony formation evaluated by MTT and soft agar assays." (PMID 22880026, 2012). "First, USP22 is a part of Polycomb/cancer stem cell signature which uniformly exhibit a marked propensity toward metastatic dissemination as well as a therapy resistance phenotype." (PMID 22880026, 2012). "In fact, USP22 is one of a small set of marker genes capable of predicting metastatic potential and therapeutic outcome in human cancer such as colorectal cancer, breast cancer, and bladder cancer." (PMID 22880026, 2012).
cancer (continued). "The precise mechanisms by which USP22 expression affects cancer progression and metastasis is unclear." (PMID 22880026, 2012). "We found that the USP22 expression increased significantly from normal mucosa to carcinomas and from carcinomas to lymph node metastasis." (PMID 22880026, 2012). "Another example is represented by USP22, which is part of a small set of marker genes capable of predicting metastatic potential and therapeutic outcome in human cancer." (PMID 21283576, 2011). "So, calycosin H10‐inhibited USP1 and USP22 should be promising targets to induce cancer cell death." (PMID 41541703, 2026). "Indeed, treatment with the proteasomal inhibitor MG132, but not the lysosomal inhibitor chloroquine, fully rescued EZH2 protein expression in cancer cells either with Usp22 deletion or treated with the USP22 small-molecule inhibitor S02." (PMID 41252204, 2025). "Usp22 inhibits MCH-I expression through upregulating EZH2 in cancer cells." (PMID 41252204, 2025). "The implication of RNF20/H2BK120ub in the formation and/or stabilization of reversed replication forks might help explain why H2BK120ub levels in cancer are frequently downregulated, due to either loss of RNF20 or upregulation of the eraser USP22." (PMID 41145912, 2025). "Ubiquitin-specific peptidase 22 (USP22) is overexpressed in various malignant tumors 112-114." (PMID 39744438, 2025). "USP22 is often overexpressed in various cancers, including NSCLC, where it may contribute to tumor progression by stabilizing oncogenic proteins and promoting cell proliferation." (PMID 40075700, 2025). "Aberrant expression of the proto-oncogene c-Myc may promote or inhibit apoptosis, and it has been shown that USP22 can increase c-Myc stability in cancer cells by deubiquitination and blocking proteasomal degradation." (PMID 40083330, 2025). "Given the importance of each of these factors in gene regulation and cancer, further delineation of USP22 functions in regulation of BRG1, PR, and GR could provide new insights to its roles in cancer formation and progression." (PMID 38236941, 2024). "Additionally, USP22 influences the cancer cell transcriptome, thereby modifying the immune tumor microenvironment." (PMID 39048965, 2024). "The trend towards increased metastasis to the lung in USP22 OE MMTV-NIC mice may indicate that USP22 facilitates downstream steps in cancer progression, such as the epithelial-mesenchymal transition." (PMID 38236941, 2024). "Evidence suggests that targeting USP22 could improve the efficacy of immune checkpoint blockade therapies, especially in cancers in which PD-L1-mediated immune evasion is a key factor." (PMID 38474186, 2024). "As the mitochondrial biogenesis program is indispensable for the CSC-based aggressive behavior in a wide range of cancer entities, we reasoned that USP22 may functionally support the mitochondrial homeostasis program." (PMID 38347585, 2024). "USP22 can stabilize proto-oncogene c-Myc, which plays a critical role in growth control, differentiation, and apoptosis and is frequently overexpressed and activated in human cancer." (PMID 37946202, 2023). "USP22 has been known to involve in tumor cell proliferation, invasion, stemness, cell cycle arrest, metastasis, immune response and drug resistance in human cancer." (PMID 37215134, 2023). "Simultaneously, elevated USP22 protein was observed in these two cancer cell lines." (PMID 37946202, 2023). "Indeed, in contrast to the fact that USP22 deletion resulted in a more than 50% reduction in lung metastases 4T1 cancer nodules, FoxM1 re-introduction restored USP22-null 4T1 cancer lung metastasis to a level of about 85–90% of the WT." (PMID 37398311, 2023). "Moreover, we validated that c-Myc upregulation is USP22-dependent, as c-Myc upregulation is abolished in USP22-Ko cancer cells." (PMID 37946202, 2023).
cancer (continued). "Therefore, USP22 is also a promising target for the development of cancer treatments because of its high expression and the critical functions in tumorigenesis of several different carcinomas." (PMID 37946202, 2023). "Therefore, like USP7, accumulating evidence indicates that USP22 also represents a promising target for cancer therapy, and USP22 knockdown markedly decreases cancer growth, induces apoptosis, and sensitizes cancer cells to chemo-radio and immune therapies." (PMID 37946202, 2023). "In addition, USP22-Ko cancer cells are more sensitive to a combination of cisplatin and USP7 inhibitor." (PMID 37946202, 2023). "The findings of our study have strongly suggested that targeting both USP7 and USP22 may represent a novel, more effective therapeutic approach for cancer treatment, which warrants further study." (PMID 37946202, 2023). "USP22 has been reported to regulate immune evasion and drug sensitivity in cancer." (PMID 37215134, 2023). "Taken together, these data suggest USP7 inhibition can synergize USP22-Ko effect in cancers." (PMID 37946202, 2023). "In addition, USP22 can deubiquitinate and stabilize programmed death-ligand 1 (PD-L1), which mediates immune suppression of cancer cells." (PMID 37946202, 2023). "In addition, USP22 has been found to deubiquitinate and stabilize PDL1 and thus cause cancer immune resistance." (PMID 35449157, 2022). "USP22 is abnormally expressed in several cancer types and facilitates tumor malignant progression." (PMID 35692754, 2022). "Targeting of USP22 is a promising new strategy to overcome drug resistance in cancer therapy." (PMID 35203285, 2022). "In PDAC, USP22 accelerates cancer cell proliferation by targeting DYRK1A." (PMID 35935969, 2022). "USP22 promoted tumor development and progression in certain cancer types." (PMID 35692754, 2022). "Regulation of USP22 expression is still poorly understood in cancer." (PMID 36123698, 2022). "Many previous studies have reported the cancer‐promoting potential of USP22, including the induction of cell proliferation and DNA repair, activation of c‐Myc/NAMPT/SIRT1‐dependent FOXO1 and YAP signaling, and deubiquitination of CD274 to suppress anticancer immunity." (PMID 34743406, 2022). "Besides, MDM2 proto‐oncogene (MDM2) inhibitor enhanced the antipancreatic cancer effects of USP22 overexpression." (PMID 34743406, 2022). "In addition, polyubiquitination of PPARγ was inhibited in USP22 highly expressed cancer tissues compared to adjacent normal tissues." (PMID 35449157, 2022). "It has been proved that USP22 is one of the significant biomarkers of cancer stem cells." (PMID 35784926, 2022). "USP22 mainly plays the role of oncoprotein in chromatin remodeling by removing ubiquitin from histones (H2B and H2A) and subsequently activates or stabilizes transcription factors in cancer progression." (PMID 35449157, 2022). "Targeting USP22 is a new strategy for potentiating anti-cancer immunity in PD-L1-amplified cancer." (PMID 35965557, 2022). "USP22 is overexpressed in a variety of tumors and plays a role in promoting cancer." (PMID 35935969, 2022). "Furthermore, we propose a new possibility of combining USP22 with chemotherapeutic, targeted, and immunosuppressive drugs in the treatment of cancer." (PMID 35935969, 2022). "USP22 affects the self-renewal of CSCs in cancer by regulating BMI1 protein expression." (PMID 35924159, 2022). "In addition, USP22 is also closely related to the development of cancers such as nasopharyngeal carcinoma, oral squamous cell carcinoma, and thyroid carcinoma." (PMID 35935969, 2022). "USP22 was considered to be involved in many cancer types as an oncogene-like protein." (PMID 35784926, 2022). "USP22 is frequently overexpressed in breast, colon, lung, and other cancers." (PMID 36123698, 2022). "In recent years, USP22 has been reported as a member of 11 “Death-from-Cancer” genes." (PMID 35784926, 2022). "USP22 regulates PD-L1 degradation in several human cancer cells." (PMID 34753387, 2021).
cancer (continued). "Overexpression USP22 is a marker of aggressive cancer phenotypes like metastasis, and therapy resistance studies have shown that catalyzing SAGA subunit USP22 to control CCND1 ubiquitination is important for the progression of cancer cells through the G1 cell cycle." (PMID 33498168, 2021). "Several E3 ligase (Cullin3-SPOP, c‐Cbl, and β-TrCP) and deubiquitinases (CSN5, USP9X, USP21, OTUB1, and USP22) have been reported to regulate PD-L1 protein degradation in cancer cells, indicating posttranslational modification plays an important roles in regulation of PD-L1 stability." (PMID 34741014, 2021). "In this regard, while USP22 has been proposed as a novel therapeutic target based on its oncogenic functions, our work suggests that USP22 inhibition will induce CIN that may promote cancer progression and/or the development of secondary malignancies." (PMID 33801331, 2021). "In addition, USP22 was chosen as a therapeutic target for reversing cancer stemness and sensitizing HCC cells to sorafenib." (PMID 33717848, 2021). "However, in recent studies, the cancer-promoting or anticancer effects of USP22 were found to depend mainly on its environment." (PMID 34179009, 2021). "Importantly, USP22 was reported to stabilize SIRT1 by deubiquitination to promote autophagy in cancer cells and also protect against ischemia–reperfusion injury in cardiomyocytes." (PMID 34759275, 2021). "Thus, our fundamental and clinical findings strongly support the possibility that reduced USP22 expression, leading to aberrant H2Bub1 regulation and CIN, are pathogenic events in many cancer types." (PMID 33801331, 2021). "Aberrant expression of ubiquitin-specific peptide 22 (USP22) has been detected in various cancers." (PMID 32063746, 2020). "Altered expression of USP22 was first detected in microarray studies from patient tissue cohorts where the expression of 11-gene signatures in stem like cells correlates with poor prognosis of the cancer." (PMID 34660907, 2020). "As expected, USP22 significantly reduced PD-L1 poly-ubiquitination in cancer cells." (PMID 32665011, 2020). "Targeting USP22 and its downstream effectors is a promising strategy in cancer therapy." (PMID 32063746, 2020). "Considering that USP22 is a stem cell marker, combination treatment with PD-L1/PD-1 blockade antibody and USP22 inhibitor might eliminate cancer stem cell." (PMID 32665011, 2020). "The positive correlation of USP22 and PD-L1 expression in human tumor samples implied the possibility that USP22 targeted therapy might be in favor of cancer treatment via PD-L1 regulation." (PMID 32665011, 2020). "Targeting of USP22 is being explored as a cancer therapeutic." (PMID 33233707, 2020). "In the majority of cancers, USP22 functions like an oncogene." (PMID 34660907, 2020). "Interestingly, by compared the in vivo angiogenesis in xenografts of USP22 knockout and the parent cancer cells, we confirmed that USP22 knockout significantly suppresses angiogenesis." (PMID 31842906, 2019). "And a slightly more γ-H2AX and H2Bub1 were still present in these USP22−/− H1299 cancer cells at 48 h post-irradition, indicating USP22 knockout impaired deubiquitination of H2Bub1 that may be required for prompt and correct DSB repair." (PMID 31842906, 2019). "Therefore, the roles of USP22 in initiation and development of various human cancers remain to be elucidated." (PMID 31842906, 2019). "Notably, through analysis the correlation of USP22 and MVD in NSCLC tissue samples, we have found a significantly positive correlation between these two stainings, indicating that elevated USP22 also promotes angiogenesis in cancer." (PMID 31842906, 2019). "Further investigations will reveal whether USP22 expression levels can serve as a prognostic marker in cancer patients where low USP22 levels can be exploited by inducing therapeutic vulnerability to HSP90i treatment." (PMID 31801945, 2019).